AGR3 (anterior gradient 3, protein disulphide isomerase family member)
Diseases named in the same sentence as AGR3 in open-access papers (continued):
Sharing a sentence is not in itself a finding about the gene and the disease.
ovarian carcinoma (5 papers, 2017 to 2025). A malignant neoplasm originating from the surface ovarian epithelium. "The expression of AGR3 was found to be associated with EsR-negative ovarian cancer." (PMID 35965326, 2022). "AGR3 was found to be expressed cytosolically in four human ovarian cancer subtypes; serous papillary, endometrioid, clear cell, and mucinous where the latter showed the highest AGR3 expression." (PMID 35965326, 2022). "Our findings demonstrate that select PDI family members (PDI, PDIR, ERp72, ERp57 and AGR3) are potential prognostic markers for ovarian cancer." (PMID 29262583, 2017). "We sought to evaluate the expression of PDI, PDIA6, PDIR, ERp57, ERp72 and AGR3 in ovarian cancer patient samples and examine their prognostic significance." (PMID 29262583, 2017). "Furthermore, AGR3 is overexpressed in several cancers, including colorectal, breast, prostate, and ovarian cancers." (PMID 40867591, 2025). "Importantly, overexpression of PDI family members is associated with poor survival in ovarian cancer (p = 0.045 for PDI, p = 0.047 for PDIR, p = 0.037 for ERp57, p = 0.046 for ERp72, p = 0.040 for AGR3) with the exception of PDIA6 (p = 0.381)." (PMID 29262583, 2017). "In conclusion, our data demonstrate that upregulation of select PDI family members can be considered as risk factors for ovarian cancer patients and PDI, PDIR, ERp57, ERp72 and AGR3 could be used as prognostic biomarkers." (PMID 29262583, 2017). "For AGR3, we observed that high expression adversely affects OS of ovarian cancer patients." (PMID 29262583, 2017). "We observed significant increases in PDI (p = 9.16E-36), PDIA6 (p = 5.51E-33), PDIR (p = 1.81E-12), ERp57 (p = 9.13E-07), ERp72 (p = 3.65E-22), and AGR3 (p = 4.56E-24) expression in ovarian cancers compared to normal tissues." (PMID 29262583, 2017). "For instance it would be interesting to investigate whether the different expression patterns of AGR3 and AGR2 in mucinous and non-mucinous (serous, endometrioid and clear cell) ovarian carcinomas could be correlated with patient prognosis." (PMID 34452625, 2021).
serous ovarian cancer (3 papers, 2015 to 2022). "In different studies, the AGR3 protein was found to be overexpressed in serous ovarian cancer and high expression of AGR3 in the serous subtype is correlated with poor prognosis." (PMID 35965326, 2022). "PDI, PDIA6, PDIR, ERp57, ERp72 and AGR3 were highly expressed in serous ovarian cancer compared to normal tissues (p = <0.001)." (PMID 29262583, 2017). "So far, the only study having considered the putative prognostic value of AGR3 reported the protein to be a biomarker of favourable prognosis in serous ovarian cancer." (PMID 25875093, 2015). "On the one hand, AGR3 was described as a marker of favourable prognosis in serous ovarian cancer, whereas a recent publication on the other hand indicated a pro-oncogenic potential for AGR3 demonstrating the mediation of cisplatin resistance by AGR3 in a H1299 cell line xenograft mouse model." (PMID 25875093, 2015).
endometrial carcinoma (2 papers, 2022 to 2023). A malignant tumor arising from the epithelium that lines the cavity of the uterine body. "Some cancer types presented more mutations than others: skin cutaneous melanomas and endometrial carcinomas for AGR2, and the same plus stomach and bladder carcinomas for AGR3." (PMID 35857928, 2022). "As far as gene expression changes are concerned, the Aldo-Keto Reductase family 1 member C3 (AKR1C3) was found to be upregulated, whereas both the Anterior Gradient Homolog 3 (AGR3) and the Nitric Oxide Synthase 2A (NOS2A) were seemingly downregulated in all three endometrial cancer cell lines." (PMID 37298140, 2023).
melanoma (2 papers, 2018 to 2025). A malignant, usually aggressive tumor composed of atypical, neoplastic melanocytes. "The AGR3/AHR posterior probability for shared genetic effects between tanning ability and CMM was 1, thus indicating that the same genetic variants are involved in both decreased tanning ability and increased risk of melanoma." (PMID 29739929, 2018).
ovarian serous carcinoma (2 papers, 2017 to 2021). "Gene expression of AGR3 in low grade ovarian serous carcinomas (LGSC), HGSC, and serous borderline tumours, showed that AGR3 is upregulated in LGSC and in serous borderline tumours as compared to regular ovarian surface, but not in HGSC." (PMID 34452625, 2021). "More importantly, PDIs overexpression in serous ovarian carcinoma correlates with patient survival, suggesting that PDI, PDIR, ERp57, ERp72 and AGR3 are potential prognostic markers for EOC." (PMID 29262583, 2017).
ovarian tumors (2 papers, 2017 to 2021). "Hence, cooperative or antagonistic biological effects could be expected, thus associating the differential expression of AGR2 and AGR3 to ovarian tumour outcomes." (PMID 34452625, 2021). "It has only been reported that AGR3 mediates cisplatin resistance in ovarian tumour xenograft, suggesting that AGR3 is pro-oncogenic and exerts functions independently of AGR2." (PMID 34452625, 2021). "Though AGR3 levels are increased in various cancers, the role of AGR3 in tumors, particularly in ovarian tumors, is poorly understood." (PMID 29262583, 2017). "We propose that AGR2 and AGR3 could exert different pro-oncogenic functions to confer specific and evolutive features to these ovarian tumours." (PMID 34452625, 2021). "In a cohort of 415 ovarian tumour tissue samples among which 238 serous tumours, 38 endometrioid tumours, 51 clear cell tumours, 32 mucinous tumours and 56 other tumour subtypes, 204 samples stained positive for AGR3, with 90% strong expression, 10% moderate expression, and no or weak expression." (PMID 34452625, 2021).
prostate carcinoma (2 papers, 2003 to 2025). A carcinoma that arises from epithelial cells of the prostate gland. "Mainly, AGR3 potentially acts as a negative regulator of AR, inhibiting the activation of genes crucial for controlling prostate cancer growth." (PMID 40265030, 2025).
chronic obstructive pulmonary disease (1 paper, 2024). A chronic and progressive lung disorder characterized by the loss of elasticity of the bronchial tree and the air sacs, destruction of the air sacs wall, thickening of the bronchial wall, and mucous accumulation in the bronchial tree. "Additionally, AGR3 positively regulates proteins involved in airway epithelial junctions in chronic obstructive pulmonary disease, suggesting its role in disrupting normal cell-cell communication in CPAM cysts." (PMID 39026356, 2024).
clear cell ovarian carcinoma (1 paper, 2017). "Our results strongly suggest that PDI, PDIA6, PDIR, ERp57, ERp72 and AGR3 expression can be useful biomarkers for clear cell ovarian carcinoma but additional studies are required to further validate the prognostic role of PDIs in these cancers." (PMID 29262583, 2017). "However, PDI, PDIA6, PDIR, ERp72 and AGR3 are more significantly overexpressed (p<0.001) than ERp57 (p<0.05) in clear cell ovarian carcinoma." (PMID 29262583, 2017). "In clear cell ovarian carcinoma PDI, PDIA6, PDIR, ERp72, ERp57 and AGR3 were overexpressed." (PMID 29262583, 2017).
cystic fibrosis (1 paper, 2025). Autosomal recessive disorder caused by pathogenic variants in the CFTR gene (cystic fibrosis transmembrane conductance regulator), which encodes a chloride and bicarbonate channel expressed in epithelial cells, and follow the diagnosis criteria. "Since AGR2 is required for proper formation of the mucociliary machinery, and AGR3 is required for calcium-mediated regulation of ciliary function, double AGR2/AGR3 knockout may exhibit severe lung phenotypes resembling those seen in cystic fibrosis." (PMID 40867591, 2025).
gastric cancer (1 paper, 2023). A primary or metastatic malignant neoplasm involving the stomach. "Finally, we identified a gene set associated with the differentiation status of gastric cancer, including AGR3, CLDN3, CLDN4, FABP1, LGALS4, PHGR1, MYH14 and S100A14." (PMID 36729271, 2023).
intrahepatic cholangiocarcinoma (1 paper, 2015). A carcinoma that arises from the intrahepatic bile duct epithelium in any site of the intrahepatic biliary tree. "Moreover, AGR3 has recently been suggested as a diagnostic marker for intrahepatic cholangiocarcinoma (ICC)." (PMID 25875093, 2015).
invasive breast carcinoma (1 paper, 2023). A carcinoma that infiltrates the breast parenchyma. "Study Selection We included observational or interventional studies, studies on AGR3 protein expression by immunohistochemistry, and studies on invasive breast cancer." (PMID 37944928, 2023).
lung adenoma (1 paper, 2025). A benign, well circumscribed epithelial neoplasm that arises from the bronchus or the lung parenchyma. "The differentially expressed genes in CPAM samples are mainly related to genes associated with airway epithelial cells, such as SCGB1A1, SCGB3A2, AGR3, and increased expression levels of these genes may be associated with proliferation and differentiation of lung adenoma cells." (PMID 40529122, 2025).
pancreatic cancer (1 paper, 2017). "Western blot analysis revealed that PDI expression is low in pancreatic cancer cells compared to other cell lines; MIA PaCa-2 cells possessed the lowest expression of PDI, ERp57, PDIA6, and AGR3." (PMID 29262583, 2017).
squamous cell carcinoma (1 paper, 2022). A carcinoma arising from squamous epithelial cells. "As a general feature, squamous cell carcinomas expressed AGR2 and AGR3 at a much lower level than adenocarcinomas (compare, for instance, LUAD with LUSC, ESCA with HNSC, CESC with UCEC)." (PMID 35857928, 2022).
ulcerative colitis (1 paper, 2012). An inflammatory bowel disease involving the mucosal surface of the large intestine and rectum. "A cohort of 2,540 patients having either ulcerative colitis or Chron’s disease was investigated for SNPs in AGR2 and AGR3; in total, 30 SNPs were identified, 25 were located in the AGR2 gene, while 5 were located in the AGR3 gene." (PMID 23245351, 2012).
cancer (24 papers, 2003 to 2025). A tumor composed of atypical neoplastic, often pleomorphic cells that invade other tissues. "Similar results were obtained for AGR3 with a lower number of cancer genes whose CNVs were associated with AGR3 than with AGR2 expression." (PMID 35857928, 2022). "Other genes within this cluster include CCDC170, WNK4 and AGR3 which have been reported to be implicated in these cancers." (PMID 30279965, 2018). "The question underlying the development of this work is whether AGR2 and AGR3 can be considered as playing a major role in oncogenesis and progression of cancers; in other terms, whether they can be considered as oncogenes and/or TSG." (PMID 35857928, 2022). "AGR3 is overexpressed by a hormone- (estrogen-receptor α-) independent mechanism and identifies a novel protein-folding associated pathway that could mediate resistance to DNA-damaging agents in human cancers." (PMID 25243088, 2014). "The disparity largely stems from the limited expression pattern of AGR3 in disease states and the resulting uncertainty regarding its pro-oncogenic potential in different cancers." (PMID 40867591, 2025). "Perhaps the least is known regarding why AGR3 is strongly selective against subsets of cancer cell lines." (PMID 40867591, 2025). "AGR3 overexpressed in PCa tissues vs benign prostate tissues and cancer/benign tissues vs tissues obtained following castration, meaning that androgens regulate these genes and are potentially involved in prostate carcinogenesis." (PMID 40265030, 2025). "The result of the meta-analysis revealed that AGR3 expression was associated with worse OS11, 13and DFS13in low- and intermediate-grade cancers." (PMID 37944928, 2023). "We performed a comprehensive analysis of available data in order to better understand the role of AGR2 and AGR3 in cancer." (PMID 35857928, 2022). "To bring some answers to this question, we have explored publicly available databases to search for relationships between genomic variations of AGR2 and AGR3 and cancer." (PMID 35857928, 2022). "In the CCLE collection, the levels of expression of AGR2 and AGR3 also vary considerably across cancer types." (PMID 35857928, 2022). "EOC represents a clinical model for evaluating the cooperative or antagonistic role of AGR2 and AGR3 in cancer and in drug resistance." (PMID 34452625, 2021). "The relationship between AGR3 and estrogen receptor expression in cancers is intriguing." (PMID 40867591, 2025). "Why ERp44, AGR2, or AGR3 are essential for specific cancer cell lines is unclear but may relate to their unique biological and biochemical functions." (PMID 40867591, 2025). "The overall conclusion of these explorations of AGR2 and AGR3 genomic variations in tumours and cancer cell lines is that it is quite unlikely that they could behave as bona fide oncogenes or TSG." (PMID 35857928, 2022). "It appears from our explorations that AGR2 and AGR3 are connected to the cancer phenotype." (PMID 35857928, 2022). "There again, similar associations were found between AGR3 expression and oncogenic mutations in these cancer types (data not shown)." (PMID 35857928, 2022). "The pattern of cell fitness alterations associated with AGR2 and AGR3 extinction are highly correlated (r = 0.331, p = 4.58 × 10−21) and did not reveal any preferential vulnerability towards a given cancer type represented in the cell line panels of the CCLE." (PMID 35857928, 2022). "Recently, we have demonstrated that extracellular AGR3 (eAGR3) has gain-of-extracellular pro-oncogenic functions within the extracellular space and could promote cancer aggressiveness." (PMID 34452625, 2021). "Moreover, AGR3 was overexpressed in many tumor tissues and could promote the stemness of cancer cells by activating Wnt/β-catenin signaling." (PMID 39026356, 2024). "For instance, in LCRC, researchers have identified a subgroup of cancer cells enriched for genes involved in maintaining of the gut lining (e.g., TFF1, TFF2, AGR3, MUC5AC)." (PMID 41450739, 2025).
cancer (continued). "The best protein biomarker combination of epithelial AGR2, AGR3, CEAM5, stromal CD90, and SFRP4 produced an AUC value of 0.95 in distinguishing cancer from non-cancer." (PMID 38595814, 2024). "The seven subclusters included alveolar cells, pathological alveolar cells expressing both normal respiratory cell markers (SFTPB, AGR3) and genes related to cancer progression (SPINK1, MET), as well as five cancer subsets." (PMID 36973297, 2023). "Among the 32 cancer types that are available in the PanCancer Atlas project of TCGA, only part of them displays a consistent expression of AGR2 and AGR3." (PMID 35857928, 2022). "To identify the tumor cells and non-tumor lung cells, we first mapped the expression of six genes (FOLR1, AGR3, and SFTPD for normal hung lung cells, and EPCAM, MDK, and SOX4 for cancer cells) to each cluster to identify the cell types in our study." (PMID 32549766, 2020). "Here, we provide a review of the literature relating to the non-canonical PDIs ERp44, AGR2, and AGR3, which have been identified as strong dependencies in specific cancer subtypes according to the DepMap database." (PMID 40867591, 2025). "In all cancer types, AGR3 was expressed at a lower level than AGR2, and often not evaluable in samples from three cancer types: BLCA, HNSC and OVCA." (PMID 35857928, 2022). "Therefore, using in silico analyses, we evaluated the expression of AGR2 and AGR3 mRNA in both the EOC cancer cell line encyclopedia (CCLE) and the EOC cancer genome atlas (TCGA) databases." (PMID 34452625, 2021). "Available data and in silico analyses demonstrated AGR3 may co-express with AGR2 or uncoupled in both human healthy tissues and carcinomas in stomach, colon, pancreas, breast, female reproductive system, or respiratory system in a tissue specific manner." (PMID 30140383, 2018). "AGR3, also referred to as breast cancer membrane protein 11 (BCMP11), has been shown being over-expressed in breast, ovarian and prostate cancer." (PMID 25875093, 2015). "We observed that three disulfide isomerases, AGR2, AGR3, and TXNDC5, are overexpressed in cancer." (PMID 25243088, 2014). "Moreover, the overexpression of AGR2 and AGR3 may be a prognosis factor for survival, which could be favourable or not favourable depending on the cancer type." (PMID 35857928, 2022).